VIM (vimentin)
Diseases named in the same sentence as VIM in open-access papers (continued):
Sharing a sentence is not in itself a finding about the gene and the disease.
endometrial cancer (continued). "Vimentin is also expressed in stromal cells and has been used solely as a stromal cell marker in endometrial cancer research." (PMID 37146405, 2023). "Whereas in AN3CA, a cell line derived from lymph node metastatic lesion of endometrial cancer, western blot showed an increase in the epithelial marker E‐cadherin, a decrease in vimentin and Zeb1." (PMID 37387559, 2023). "ZEB2 can trigger EMT in endometrial cancer by raising vimentin levels while decreasing E-cadherin expression." (PMID 35992812, 2022). "Five most significant genes were selected, including L1CAM (L1 cell adhesion molecule), PRKCI, ESR1, CDKN2A and VIM, to construct a prognostic model for endometrial cancer." (PMID 34659539, 2021). "Grade 2 (G2) and Grade 3 (G3) EC cases also exhibit variable vimentin and keratin expression, indicating that the value of IHC for vimentin and keratin is limited in endometrial cancer diagnosis." (PMID 35002543, 2021). "PGC-1α and vimentin in different myometrial invasion of pre- and post-menopausal endometrial cancer." (PMID 32920551, 2020). "Spearman correlation analysis showed that the expression of PGC-1α in premenopausal endometrial cancer patients was positively correlated with that of vimentin (r= 0.344, P = 0.027)." (PMID 32920551, 2020). "Spearman correlation analysis showed that the expression of PGC-1α in endometrial cancer was positively correlated with that of vimentin (r= 0.263, P = 0.018)." (PMID 32920551, 2020). "Still, SFN has been shown to increase E-cadherin and decrease N-cadherin and vimentin expression in endometrial cancer cells." (PMID 33218199, 2020). "More in details, P4 modulates TGF-β signaling in endometrial cancer cells at ligands, receptors, and Smads levels, thus inhibiting invasiveness as a consequence of an increase in E-cadherin and a decrease in Vimentin expression." (PMID 28630448, 2017). "Stable silencing of BMI-1 in invasive mesenchymal endometrial cancer cells was shown to downregulate vimentin, and significantly reduced cell invasion in vitro." (PMID 28968963, 2017). "In endometrial cancer, miR-194 was also found to have a protective effect, increasing levels of E-cadherin and reducing levels of vimentin, thus inhibiting cellular invasion via its regulation of the protein BMI-1." (PMID 26909612, 2016). "Tumor xenografts were stained for markers of EMT including cytokeratin, vimentin, and E-cadherin and compared with normal endometrium, hyperplastic endometrium, and grade 1 endometrial cancer." (PMID 25542024, 2014). "Grade 1 endometrial cancer and hyperplasia tissues were weakly positive for vimentin in both epithelium and stromal cells." (PMID 25542024, 2014). "In our series amongst 13 HPV negative samples, the endocervical origin seems probable in five CEA positive samples while two vimentin positive samples are suspected to be endometrial cancer." (PMID 20199664, 2010). "The use of various micro-RNAs (miRNAs) targeting the Notch pathway hindered the proliferation of the CD44/CD133-positive subpopulation in endometrial cancer (miRNA134), limited the expression of vimentin (VIM), reduced EMT, and decreased tumour formation and invasiveness (miRNA-34a)." (PMID 38539419, 2024). "This is to our knowledge the largest study of vimentin expression in endometrial cancer." (PMID 39516342, 2024). "The functional mechanism of vimentin in endometrial cancer should be further explored." (PMID 37146405, 2023). "Importantly, we identified vimentin expression in epithelial cells to be a robust marker for recurrence in low-stage endometrial cancer." (PMID 37146405, 2023).
endometrial cancer (continued). "The progestogen medroxyprogesterone acetate has also been shown to decrease migration, invasion, and vimentin expression in endometrial cancer cells expressing progesterone receptor B or progesterone receptors A and B, though not in those expressing progesterone receptor A alone." (PMID 36052252, 2022). "Additionally, in vitro studies reveal that metformin decreases endometrial cancer cell migration and invasion and influences epithelial marker expression with increased E-cadherin and decreased N-cadherin, vimentin, and fibronectin." (PMID 36052252, 2022). "The expression patterns of vimentin and ERα in endometrial cancer samples were examined by IHC." (PMID 34659539, 2021). "Similarly, our study showed that 10 μM of ISL reduced TGF-β1-induced expression of N-cadherin, vimentin, and p-Smad3, while increased E-cadherin expression, and finally inhibited the migration of endometrial cancer cells." (PMID 33799801, 2021). "We observed that Piwil1 could downregulate epithelial marker E-cadherin and upregulate mesenchymal markers Vimentin and N-cadherin in endometrial cancer cells." (PMID 26506848, 2015). "Besides, EFEMP1 increased expression of E-cadherin and suppressed expression of vimentin in endometrial carcinoma." (PMID 23840707, 2013). "Overall, the inhibition caused by the emmprin siRNA affected cell proliferation, migration and invasion through TGF-β, EGF, NF-κB, VEGF, MMP-2 and MMP-9 expression, which in turn resulted in increased levels of E-cadherin and reduced levels of Vimentin and Snail in endometrial cancer." (PMID 22640183, 2012). "Emmprin knockdown by the siRNA led to cell proliferation, migration and invasion through TGF-β, EGF, NF-κB, VEGF, MMP-2, and MMP-9 expression, which in turn resulted in increased levels of E-cadherin and reduced levels of Vimentin and Snail in endometrial cancer." (PMID 22640183, 2012). "However, the functional role of vimentin in endometrial cancer remains unknown, necessitating further functional studies." (PMID 39516342, 2024). "It has been reported that ASCs can fuse with endometrial cancer cells, and the fused endometrial cancer cells present a fibroblast-like appearance of mesenchymal phenotype accompanied by downregulation of E-cadherin expression and upregulation of Vimentin expression." (PMID 31440472, 2019). "CD147 may reduce e-cadherin level and increase vimentin and snail levels in endometrial cancer." (PMID 25268615, 2014). "We have revealed that silencing of ZEB2 can effectively make endometrial cancer cells more sensitive to Paclitaxel treatment and lead to the downregulation of Twist1, MMP2, and vimentin and upregulation of E-cadherin." (PMID 35992812, 2022). "Taken together, our results constructed a circ_0007534/miR-625/ZEB2 signaling, which drives endometrial cancer progression and chemoresistance by modulating several key EMT-related genes, including Twist1, MMP2, E-cadherin, and Vimentin." (PMID 35992812, 2022). "However, the function of vimentin in endometrial carcinoma (EC) remains unclear." (PMID 35320951, 2022). "CAFs isolated from endometrial cancer tissues were highly positive for α-SMA, FSP1, and FAP expression and moderately positive for vimentin expression, and were found to play diverse roles in endometrial tumor progression." (PMID 33808627, 2021). "Vimentin and PGC-1α expression levels were statistically different in pre- and postmenopausal endometrial cancer (P = 0.006 and P= 0.030, respectively)." (PMID 32920551, 2020). "PIWIL1 promotes endometrial cancer stem cell development through endometrial EMT as over-expression of PIWIL1 increases N-cadherin and vimentin and decreases E-cadherin gene expression." (PMID 30719208, 2019). "The Hec50 and AN3CA cell lines represent aggressive type 2 endometrial cancers that have lost epithelial markers including E-cadherin and ESR1 and gained mesenchymal markers such as N-cadherin and vimentin, indicative of EMT." (PMID 21501518, 2011).
endometrial cancer (continued). "Wound healing assay and Transwell migration assay results showed that RNA interference targeting NRDR gene expression could promote the migration of endometrial cancer cells and the expression of α-SMA, Vimentin, and Twist." (PMID 40661182, 2025). "CAF markers that have been identified in endometrial cancer include α-SMA, FSP1, FAP, and vimentin." (PMID 33808627, 2021). "To further explore the mechanism underlying the effect of TMEFF1 on the invasion and migration of endometrial carcinoma cells, we used western blot to determine the changes in the key EMT proteins E-cadherin, Vimentin, MMP2, and MMP9 between before and after TMEFF1 knockdown." (PMID 34475991, 2021). "Worse patient prognosis with decreased vimentin expression may indicate that endometrial cancer cells with lower levels of vimentin are less similar to normal endometrial cells and are more malignant." (PMID 37146405, 2023). "On the other hand, in certain malignancies such as endometrial cancer, the lack of vimentin expression has been correlated significantly with lymph node metastasis, deep myometrium invasion, lymph vascular space invasion, advanced stages (III and IV), and higher tumor grade." (PMID 36769377, 2023). "The results of this study demonstrated that ISL could reverse TGF-β-induced endometrial cancer cell migration through inhibition of TGF-β/Smad signaling pathway with subsequent increased E-cadherin expression and reduced N-cadherin, vimentin, α-SMA, p-Smad3, and TWIST1/2 expression." (PMID 33799801, 2021). "Both preclinical studies demonstrate that ISL could inhibit TGF-β/Smad-induced endometrial cancer cell migration through reducing p-Smad2/3 and TWIST1/2 expression, subsequently decreasing N-cadherin, vimentin, α-SMA while increasing E-cadherin protein expression." (PMID 33799801, 2021). "Similarly, vimentin expression was related to the depth of myometrial invasion of premenopausal endometrial cancer (P = 0.009), but not to that of postmenopausal endometrial cancer (P = 0.064)." (PMID 32920551, 2020). "In endometrial cancer, CK (AE1/AE3) and vimentin are positive, while CD68 is negative, and the Ki67 proliferation index is significantly greater than that in malacoplakia." (PMID 38895183, 2024). "Thus, endocervical origin seems confirmed in some samples, endometrial cancer were suspected in four others (two vimentin positive and two without conclusive IHC results but were serous ADC) and one could not be further classified due to lack of histological or IHC markers." (PMID 20199664, 2010). "This indicates that vimentin expression is not related to increased invasiveness and could be a poor marker for EMT in endometrial cancer." (PMID 37146405, 2023). "In the present study, it was observed that culture of the IKPRB-1 and IKPRAB-36 endometrial cancer cell line, but not IKPRA-1, in the presence of MPA resulted in inhibition of migration and down regulation of the mesenchymal marker vimentin at the edge of a manually inflicted wound." (PMID 22295114, 2012).
oral cancer (42 papers, 2009 to 2026). "Increased vimentin and decreased E-cadherin expression in oral cancers are associated with metastasis and disease progression." (PMID 38540309, 2024). "We evaluated the changes in EMT-associated E-cadherin and vimentin in highly invasive oral cancer cells." (PMID 24931737, 2014). "Furthermore, it will be interesting to investigate if any of these risk factors directly regulate levels of vimentin in oral cancer." (PMID 35207438, 2022). "An up-regulation of IVL after RNAi-based VIM depletion was found in malignantly transformed oral cancer cells." (PMID 39682709, 2024). "We and others have shown that vimentin positivity in the late stages of oral cancers correlates with poor prognosis." (PMID 35207438, 2022). "Nonetheless, more studies correlating vimentin expression in early and late cancerous lesions of the oral cavity to the disease free-survival in a large number of patients are required to establish vimentin as a marker for poor prognosis in oral cancers." (PMID 35207438, 2022). "The literature cited here shows a high promise in investigating vimentin as a potential biomarker candidate for oral cancer, since its expression correlates as well as contributes to the process of oral oncogenesis." (PMID 35207438, 2022). "Our laboratory has also shown the prognostic significance of vimentin in oral cancer and premalignancy." (PMID 35330094, 2022). "In this review, we have described studies on vimentin in oral cancers, to make a compelling case for vimentin as a prognostic biomarker." (PMID 35207438, 2022). "Our studies on a premalignant oral cancer cell line showed that forced expression of vimentin in the early stages of cancer is advantageous for the transformation of the cancer cell." (PMID 35207438, 2022). "The vimentin expression is useful as both poor prognostic and early detection marker in oral cancer." (PMID 35498535, 2022). "As the fourth step, we have evaluated the vimentin expression in saliva as a noninvasive means and have shown that vimentin can be a good marker for both early detection and disease monitoring in oral cancers." (PMID 35498535, 2022). "As a driver towards acquiring stemness-related signatures in premalignant oral cancer lesions, our lab has shown a critical role of vimentin in the development and progression of oral cancers." (PMID 35207438, 2022). "Results from another group suggested that the silencing of Sox2 suppressed drug-resistance and anti-apoptotic genes, and they observed that the expression level of Snail, Slug, Twist, and vimentin were repressed in the CSCs of oral cancer." (PMID 35682836, 2022). "The role of vimentin was further evaluated in oral precancers and in saliva indicating that vimentin can be a very useful marker in oral cancer for determining prognosis and can be used for early detection of the disease in saliva and oral precancer tissues." (PMID 35498535, 2022). "Consistent with findings from these studies in oral cancers, vimentin was shown as a prognosticator of disease recurrence with a risk ratio of 3.5 in advanced colorectal cancers." (PMID 35207438, 2022). "Our previous work shows that vimentin is involved in reprogramming the epithelial state to a more mesenchymal state by controlling the expression of keratin pair of K5/K14 in an oral cancer-derived cell line." (PMID 35207438, 2022). "The current study showed the aberrant vimentin expression in oral premalignant lesions and oral cancers." (PMID 35498535, 2022). "We wanted to evaluate if vimentin can be a biomarker for oral cancers, comprising of both the major sites buccal as well as tongue." (PMID 35498535, 2022). "OSF significantly induced the EMT in oral cancer cells and downregulated epithelial markers, such as E‐cadherin, but significantly elevated vimentin, fibronectin, N‐cadherin, RhoA, Rac‐1 and FAK." (PMID 34528373, 2021).
oral cancer (continued). "In contrast, the expression of mesenchymal cell-biased markers such as N-cadherin and vimentin was significantly promoted in oral cancer cells." (PMID 34335946, 2021). "In turn, a reduction in the level of vimentin was observed in PL-treated oral cancer cells (CGHNC8)." (PMID 32635287, 2020). "In this study, ROS scavenger NAC treatment led to the increase in E-cadherin expression and the decrease in p-Akt, Snail, and Vimentin levels in oral cancer cells." (PMID 29725496, 2018). "In this report, melatonin abated the migration and invasion of oral cancer cells, downregulated the expression of p-Akt, Vimentin, and Snail, and upregulated E-cadherin level in vitro and in vivo." (PMID 29725496, 2018). "In our previous study, we showed that down‐regulated vimentin and down‐regulated E‐cadherin expression was found in the oral cancer cells at the invasive front." (PMID 29150940, 2018). "Consistently, in this work, Akt activation was parallel with the increase of Snail and Vimentin and the decrease of E-cadherin in oral cancer cells." (PMID 29725496, 2018). "Melatonin inhibited the migration and invasion of oral cancer cells by repressing ROS-activated Akt signaling, implicating with the reduction of Snail and Vimentin and the enhancement of E-cadherin." (PMID 29725496, 2018). "To determine if vimentin expression correlates with lymph node metastasis in oral cancer, we examined vimentin protein levels in 85 primary OSCC samples by immunohistochemistry (IHC) staining analysis." (PMID 27966589, 2016). "The DNMT3b silencing vector induced oral cancer cells to increase their epithelial characteristics as determined by changes in expression of E-cadherin, a hallmark of EMT and vimentin." (PMID 24625449, 2014). "Oral carcinoma tissue samples were found to have significantly higher levels of vimentin and pAKT expression than their controls." (PMID 22912735, 2012). "In oral cancer, expression of Vimentin significantly increases in groups stratified by tumor satellite distance." (PMID 23076115, 2012). "In summary, we demonstrated that Akt inhibition by PIA treatment induced downregulation of Snail and Twist expression, upregulation of E-cadherin and β-catenin, downregulation of vimentin, and reduced cell migration, which led to the MErT in oral cancer cells." (PMID 19243631, 2009). "Apoptosis, causing cell cycle arrest in G2/M phase and suppression of oral cancer progression; reduction in cancer cell migration and invasion by upregulation of E-cadherin and downregulation of N-cadherin and vimentin; therapeutic agent for treating oral cancer." (PMID 39518052, 2024). "Vimentin secretion in saliva could be detected as significantly high in oral cancer and precancer patients." (PMID 35498535, 2022). "Likewise, overwhelming research from various groups show a substantial contribution of vimentin in oral cancer progression." (PMID 35207438, 2022). "The expression of K5/14 and vimentin correlated with a poor prognosis of oral cancer patients." (PMID 35330094, 2022). "Interestingly, vimentin was significantly correlated to the dedifferentiated state of the oral precancers with oral cancers (p ≤ 0.001; χ2 = 77.037)." (PMID 35498535, 2022). "We have previously identified both EpCAM and CD24 as CSC markers that, alongside the mesenchymal marker Vimentin, identify EMT CSCs in human oral cancer cell lines." (PMID 37975646, 2023). "Increased CDH1 and reduced CDH2 and VIM levels support the beneficial effect of ELLB in inhibiting cell migration and EMT in oral cancer cells." (PMID 36761830, 2022). "Treatment with Akt inhibitor LY294002 enhanced E-cadherin expression and reduced Snail and Vimentin levels, indicating that Akt activation-induced EMT promotes oral cancer cell migration and invasion." (PMID 29725496, 2018).